GPX4 (glutathione peroxidase 4)
Diseases named in the same sentence as GPX4 in open-access papers (continued):
Sharing a sentence is not in itself a finding about the gene and the disease.
endometriosis (14 papers, 2020 to 2025). The growth of functional endometrial tissue in anatomic sites outside the uterine body. "Parameters examined include ferritin and GPx4 levels, as well as the stage of endometriosis according to the Association of Gynecologic Laparoscopists (AAGL) classification." (PMID 39910174, 2025). "Our study is, to the best of our knowledge, the first study to use SNP genotypic assay to compare the distribution of the SNP rs713041 alleles on GPX4 gene between endometriosis patients and healthy controls in a Han population." (PMID 32679649, 2020). "In conclusion, our findings imply that the genetic polymorphism of the GPX4 gene likely contributes to the pathogenesis of endometriosis." (PMID 32679649, 2020). "Nonetheless, even if the control group has some women with occult endometriosis, the difference between endometriosis and endometriosis-free patients in the allele frequency for SNP rs713041 of GPX4 is still significant." (PMID 32679649, 2020). "Women who have advanced stage endometriosis were different from mild endometriosis in genetic variants of GPX4 gene (p = 0.001)." (PMID 32679649, 2020). "Regarding the GPX4 (rs713041) SNP, there was a significant difference in allele frequency between endometriosis and control groups and between the early and advanced stages of endometriosis groups." (PMID 32679649, 2020). "The findings of our study indicated that genotype GPX4 rs713041 may be associated with not only the occurrence but also the severity of endometriosis." (PMID 32679649, 2020). "In addition, the SNP GPX4 (rs713041) was associated with the severity of the endometriosis." (PMID 32679649, 2020). "MenSC-EV treatment normalised oxidative-stress indices (SOD1, GPX4), restored PR-B expression, and decreased lesion area by more than 60% in mice with endometriosis." (PMID 41296460, 2025). "Understanding the roles of ferritin and GPx4 in the pathophysiology of endometriosis tissue can potentially lead to therapeutic strategies targeting cell death pathways." (PMID 39910174, 2025). "Our study revealed a significant downregulation of GPX4 in stromal cells of endometriosis patients (M = 59.7% ± 42.4 versus 90.0% ± 17.5 in the control group, t = −2.90, p = 0.005)." (PMID 39062590, 2024). "Endometriosis is characterized by iron-dependent lipid peroxide accumulation and ferroptosis resistance through the up-regulation of redox enzymes, GPx4, and SOD." (PMID 37296777, 2023). "Exposure of embryos to endometriosis PF resulted in a significant reduction in GPX4 expression, which was consistent with the IF staining results." (PMID 34782602, 2021). "Iron overload in endometriosis PF disrupted blastocyst formation, decreased GPX4 expression and induced lipid peroxidation, suggesting that iron overload causes embryotoxicity and induces ferroptosis." (PMID 34782602, 2021). "Mouse embryos cultured with endometriosis PF exhibited decreased GPX4 expression, which uses glutathione to selectively detoxify lipid hydroperoxides and acts as a gatekeeper for ferroptosis." (PMID 34782602, 2021). "In the codominant genotypic test model, the CC, CT and TT genotype frequencies of GPX4 (rs713041) were 33 (36.7%), 38 (42.2%) and 19 (21.2%) in endometriosis cases, and 22 (16.9%), 72 (55.4%), 36 (27.7%) in the control group, respectively (p = 0.004, X2 test)." (PMID 32679649, 2020). "In conclusion, the relationship between endometriosis and SNP of antioxidant enzymes, GPX4 and TXN2, was confirmed by the present study." (PMID 32679649, 2020). "Previous studies regarding endometriosis and GPX4 relations composed mostly quantitative protein concentration measurement found in serum, peritoneal fluids or ectopic endometrial tissues." (PMID 32679649, 2020). "In the recessive test model, the CC and CT/TT genotype frequencies of GPX4 (rs713041) were 33 (36.7%), and 57 (63.3%) in endometriosis cases, and 22 (16.9%), and 108 (83.1%) in the control group, respectively (p = 0.001, X2 test)." (PMID 32679649, 2020).
endometriosis (continued). "This prospective case-control study attempted to check the connection between single nucleotide polymorphism (SNP) of three antioxidant enzymes (glutathione peroxidase 4 (GPX4), thioredoxin 2 (TXN2), thioredoxin reductase 1 (TXNRD1)) and endometriosis." (PMID 32679649, 2020). "Patients with advanced stage endometriosis featured a higher frequency in the CC genotype of GPX4 rs713041 than that of stage I-II patients." (PMID 32679649, 2020). "A recent study revealed an inverse correlation between ferritin and GPX4 levels in endometriosis." (PMID 40911580, 2025). "In endometriosis, there is a distinct pattern of iron-dependent lipid peroxide buildup and increased resistance to ferroptosis, facilitated by the upregulation of redox enzymes like glutathione peroxidase 4 (GPx4) and superoxide dismutase (SOD)." (PMID 39199287, 2024). "To further confirm that endometriosis PF can decrease GPX4 expression in embryos, we also conducted automated capillary-based simple western immunoblots to detect the embryonic expression of GPX4." (PMID 34782602, 2021). "According to the result, we suggested that the GPX4 might contribute to the pathogenesis of endometriosis." (PMID 32679649, 2020). "The results revealed GPX4 (rs713041) has a significantly different distribution between two groups (C:T = 116 (44.6%):144 (55.4%) in control and C:T = 104 (57.8%): 76 (42.2%) in endometriosis groups, p = 0.007)." (PMID 32679649, 2020). "In this study, we compared the genetic variation of three antioxidant enzymes, GPX4, TXN2 and TXNRD1 and attempted to identify whether there is any difference in allele frequency between endometriosis and control patients." (PMID 32679649, 2020). "Our results suggest that a difference in rs713041 (CC vs. CT + TT) of GPX4 may be a reason for the occurrence and severity of endometriosis." (PMID 32679649, 2020). "In an attempt to answer this question, this study compared the genetic variants of three different oxidative stress enzymes (GPX4, TXN2 and TXNRD1) and evaluated if there is a difference in genotype and allele frequency between women with endometriosis and healthy controls." (PMID 32679649, 2020). "This suggests a difference in genotypes of GPX4 (rs713041) may play a role in pathogenesis of endometriosis." (PMID 32679649, 2020). "In addition to disrupting mitochondrial function, the iron-overload environment in the peritoneal fluid of endometriosis could also reduce the expression of GPX4 and induce lipid peroxidation." (PMID 37607902, 2023). "While a comparison of GPX concentration between mild endometriosis and controls is not available from our study, we found that there is a significant difference of allele frequency in GPX4 rs713041 SNP between early (stage I–II) and advanced (stage III–IV) stages of endometriosis." (PMID 32679649, 2020). "Compared to normal human endometriosis cells, the expression of BAK1, CHMP2A, GPX4, and GSDMD was upregulated, whereas the expression of CHMP2B, IRF2, and TIRAP was negatively regulated in UCEC cells." (PMID 40535818, 2025). "This retrospective case–control study provides a comprehensive immunohistochemical assessment of the expression and tissue distribution of established ferroptosis markers: GPX4, ACSL4, and TfR1 in endometriosis patients." (PMID 39062590, 2024). "The granulosa cells of women with endometriosis had increased MDA, a metabolite of LPO products, but decreased regulatory inhibitors of the ferroptosis activation pathway (e.g., glutathione and GPx4) compared with controls." (PMID 37296777, 2023). "Further research with a larger sample size and preferably immunnohistological stains for GPX4 and TXN2 expression is warranted to understand their roles in development of endometriosis." (PMID 32679649, 2020). "Ferritin and GPx4 levels were not measured for all findings of endometriosis lesions in other organs so that they did not describe the condition of ferritin and GPx4 levels as a whole." (PMID 39910174, 2025).
endometriosis (continued). "Thorough, prospective studies are crucial to validate promising biomarkers such as glutathione, malondialdehyde, ORP, and GPX4 activity, as well as to evaluate targeted medications in specifically defined patient populations, including women with PCOS, reduced ovarian reserve, and endometriosis." (PMID 41226419, 2025).
lymphoma (14 papers, 2011 to 2025). A malignant (clonal) proliferation of B- lymphocytes or T- lymphocytes which involves the lymph nodes, bone marrow and/or extranodal sites. "EBV infection activates lipid metabolism and induces ferroptosis, which may serve as a potential therapeutic strategy for EBV-associated lymphomas.It triggers ferroptosis by promoting lipid peroxidation while simultaneously upregulating Gpx4 to confer resistance to ferroptosis in NPC cells." (PMID 40170865, 2025). "We analyzed GPX4's expression levels in normal control group tissue and lymphoma tissue, and performed ROC curve analysis." (PMID 38333875, 2024). "GPX4, an antioxidant enzyme, mitigates lipid peroxidation in lymphoma and hence is a central repressor of ferroptosis." (PMID 38007476, 2023). "Squalene accumulation in cholesterol auxotrophic lymphomas inhibits oxidative cell death by Gpx4 induction." (PMID 35326231, 2022). "In summary, targeting SCARB1 with HDL NPs in cholesterol uptake–addicted lymphoma cells abolishes GPX4, resulting in cancer cell death by a mechanism consistent with ferroptosis." (PMID 33208460, 2021). "Expression of the tumour suppresser gene TXNIP increased, while GPX1 and GPX4 expression, which are related to poor prognosis of lymphoma patients, decreased." (PMID 33451071, 2021). "A comprehensive examination by two pathologists reported that a similar percentage of Gpx4+/− and control mice (55–60%) had neoplastic disease, although an age-related delay in fatal lymphoma was seen in Gpx4+/− mice." (PMID 21115536, 2011). "Firstly, GPX4 blocks the cell cycle's S-phase and inhibits lymphocyte proliferation, while also inhibiting the expression of 16 key upregulated pathogenic genes in inhibiting CDCA7 gene's expression significantly and lymphoma." (PMID 38333875, 2024). "Finally, when comparing these donor-derived CD4 T-cells with lymphoma-derived cell lines, common features emerged, most notably the high expression of GPX4, TXNRD1 and SELENOT transcripts." (PMID 35163318, 2022). "In conclusion, we report that HDL NPs target SCARB1 in cholesterol uptake–dependent and GPX4-dependent lymphoma cells revealing an apparent reciprocal oncometabolic response favoring an increase in de novo cholesterol biosynthesis at the expense of GPX4 expression." (PMID 33208460, 2021). "However, the mRNA level of GPX1 and GPX4 decreased by a different degree in all three lymphomas cell lines." (PMID 33451071, 2021). "Accordingly, our group explored whether HDL NP therapy targeting SCARB1 induced lymphoma cell death through a mechanism involving GPX4 and ferroptosis." (PMID 33208460, 2021). "Our data show that reduced GPX4 expression leads to an increase in membrane-oxidized lipids and cell death through a mechanism consistent with ferroptosis in cell lines, in an in vivo xenograft model, and in primary samples obtained from patients with lymphoma." (PMID 33208460, 2021). "Seven selenoproteins, that included TXNRD1, GPX1, GPX4, SELENOH, SELENOO, SELENOS and SELENOT, were detected in both lymphoma-derived and primary CD4 T cells." (PMID 35163318, 2022). "Ferroptosis-related proteins GPX4, HADHB, and SECISBP2 can be prognostic biomarkers of lymphoma." (PMID 38007476, 2023). "As this metabolic profile is not unique to lymphomas, it is possible that HDL NPs may have translational relevance in a range of cholesterol-addicted cancers that are sensitive to cell death by ferroptosis following GPX4 depletion." (PMID 33208460, 2021).
psoriasis (14 papers, 2021 to 2026). An autoimmune condition characterized by red, well-delineated plaques with silvery scales that are usually on the extensor surfaces and scalp. "Multiple enriched psoriasis-associated signaling pathways were also detected in the Krt14/Gpx4 model." (PMID 39570671, 2024). "Activation of Stat3, Erk, and Akt, signaling pathways implicated in psoriasis and indicative of KC proliferation, was detected in K14/Gpx4 epidermis." (PMID 39570671, 2024). "Taken together, our results suggest that ferroptosis of a subset of K14+ KCs, induced by Gpx4 deficiency, is sufficient to initiate and maintain a T cell–dependent psoriasis-like phenotype in the K14/Gpx4 model." (PMID 39570671, 2024). "As selenium, a crucial element for GPX4 synthesis, is found deficient in psoriasis patients, this could potentially explain the decreased antioxidant capacity and increased susceptibility to ferroptosis in these individuals." (PMID 39430757, 2024). "Comparison of the K14/Gpx4 transcriptional profile with that of human psoriatic skin revealed 531 shared differentially expressed genes (DEGs), 426 of which showed positive correlation, including those genes associated with psoriasis and ferroptosis." (PMID 39570671, 2024). "K14/Gpx4 mice also developed signs of psoriasis-associated systemic inflammation — elevated serum proinflammatory cytokines (e.g., IL-6), an increase of splenic CD4+ and CD8+ T cells, CD4+ T cell infiltration of the hind-paw synovium, neutrophilic infiltration of the liver and the lungs." (PMID 39570671, 2024). "Analyses of the skin of K14/Gpx4 mice revealed parakeratosis and acanthosis with elevated epidermal proliferation index, mixed dermal immune cell infiltrate including T lymphocytes, clusters of neutrophils in the epidermis, and upregulation of psoriasis-associated cytokines and lipid mediators." (PMID 39570671, 2024). "Selenium deficiency affects GPX4 biosynthesis, and selenium levels are decreased in patients with psoriasis with longer disease durations and are correlated with psoriasis severity, which may explain the reduced antioxidant activity and susceptibility to ferroptosis in patients with psoriasis." (PMID 39358326, 2024). "It is observed that selenium was decreased and related to the severity of psoriasis in patients with long disease duration, and selenium deficiency affects the biosynthesis of GPX4, which might explain the decreased antioxidant activity and susceptibility towards ferroptosis in psoriatic patients." (PMID 36188212, 2022). "Compared to healthy skin, the iron content in the skin cells of psoriasis patients increases, while the expression of GPX4 is downregulated." (PMID 41226498, 2025). "In another study, it was also found that the GPX4 in keratinocytes of psoriasis patients was significantly reduced, and lipid peroxidation was enhanced." (PMID 41226498, 2025). "Several studies have demonstrated that there is a significant reduction in intracellular GPX4 levels following inflammation, which is consistent with findings observed in psoriasis." (PMID 40699725, 2025). "Among the considered mouse models, K14/Gpx4 and idIL-23 showed the most significant correlations with the human psoriasis transcriptome." (PMID 39570671, 2024). "Of these, GPX4, an essential antioxidant enzyme, appears to have a reduced role in psoriasis pathogenesis." (PMID 39430757, 2024). "Overall, these results demonstrate concordance of transcriptional changes in K14/Gpx4 skin and human psoriasis." (PMID 39570671, 2024). "Simultaneously, by targeting the activity of key enzymes such as GPX4, it can induce pathological skin cells to undergo ferroptosis, offering a novel therapeutic approach to control the progression of psoriasis." (PMID 39430757, 2024). "Vitamin D, essential in skin homeostasis, is routinely used to treat psoriasis, and was previously shown to inhibit ferroptosis and increase Gpx4 expression." (PMID 39570671, 2024).
psoriasis (continued). "Psoriasis skin-derived S.B cells expressed GPX4, FTL, and FTH1 at high levels, whereas control skin-derived S.G & S.S cells expressed high levels of GPX4, FTH1, NR4A1, NFE2L2, and MT1G." (PMID 35962439, 2022). "The levels of MDA, nitric oxide, ROS, and epidermal iron in psoriasis patients increased, while the levels of superoxide dismutase, glutathione peroxidase activity, GPX4 expression, and total antioxidant capacity decreased." (PMID 34707088, 2021). "In normal samples, GPX4 was significantly expressed in all layers of the epidermis, whereas in the psoriasis skin, GPX4 was barely expressed." (PMID 34707088, 2021). "We next asked whether the K14/Gpx4 model recapitulates the gene expression profile of psoriasis and performed RNA-Seq of K14/Gpx4 lesional skin versus Cre– control skin." (PMID 39570671, 2024). "In addition, administrations of a ferroptosis inhibitor, Lip-1, not only prevented the emergence of psoriasis, but also successfully treated an established psoriasiform dermatitis and systemic inflammation of K14/Gpx4 mice receiving TMX." (PMID 39570671, 2024). "Transcriptional profile concordance between K14/Gpx4 model and human psoriasis." (PMID 39570671, 2024). "Such an epithelial-immune microenvironment dysregulation is at the center of chronic inflammatory diseases of the skin and other organs, and our K14/Gpx4 model successfully integrates KC-centric and immune hypotheses of psoriasis pathogenesis." (PMID 39570671, 2024). "We found that K14/Gpx4 mice developed a phenotype highly resembling psoriasis." (PMID 39570671, 2024). "To test for a similar effect in vivo, we checked whether topical application of pro-ferroptosis inhibitors of Gpx4 or the cystine-glutamate antiporter system xc– would produce a psoriasis-like phenotype in mice." (PMID 39570671, 2024). "Furthermore, our K14/Gpx4 model demonstrates that both ferroptosis of some KCs and subsequent T cell–mediated immune responses are required to maintain epidermal lipid redox dysregulation and chronic inflammation of psoriasis." (PMID 39570671, 2024). "Factors that lead to diminished levels of Gpx4 in psoriasis remain unknown." (PMID 39570671, 2024). "Ferroptosis, driven by iron-dependent lipid peroxidation and dysfunction of Glutathione peroxidase 4 (GPX4), emerges as a relevant cell death pathway, particularly in psoriasis and atopic dermatitis (AD)." (PMID 42278195, 2026). "To better delineate the role of K14+ KC ferroptosis in psoriasis, we generated a tamoxifen-inducible (TMX-inducible) genetic mouse model, K14-CreERT+/+ Gpx4fl/fl (referred to henceforth as K14/Gpx4), with Gpx4 depletion in K14-expressing KCs." (PMID 39570671, 2024). "The expression of GPX4 and ACSL4 were detected in psoriasis lesions and normal samples by immunohistochemistry." (PMID 34707088, 2021). "Similarly, the upregulation of PTGS2 and TFRC expression and decreased FTL, GPX4, and FTH1 mRNA levels were observed in psoriasis samples." (PMID 39308857, 2024). "In addition, some critical ferroptosis suppressor genes, such as GPX4, FTL, and FTH1, are expressed at high levels in the keratinocyte population in psoriasis." (PMID 35962439, 2022). "For example, GPX4 was highly expressed in all layers of the epidermis in normal samples while under-expressed in psoriatic skin, and ACSL4 was highly expressed in the basal layer of the epidermis in psoriasis compared to the normal skin." (PMID 36188212, 2022). "However, the expression of key regulators in ferroptosis (SLC7A11and GPX4) suggested that ferroptosis was inhibited in psoriasis, which was not explained in this study." (PMID 36276287, 2022).